MRGBP (MRG domain binding protein)
Diseases named in the same sentence as MRGBP in open-access papers (continued):
Sharing a sentence is not in itself a finding about the gene and the disease.
cancer (continued). "As a result, we observed accumulated MRGBP mainly in the nucleus of cancer cells in 20 out of the 27 tumours." (PMID 20051959, 2010). "However, some amplified genes in treated HEK293T (e.g., BMP7, MRGBP, CDH12) are associated with EMT in PDAC and other cancer types." (PMID 36289850, 2022). "Much of the research indicated an oncogenic role of MRGBP in the development of cancers." (PMID 34660575, 2021). "However, the role of MRGBP in tumors has only been studied in a few tumors, and the link between MRGBP and various cancers deserves to be investigated." (PMID 34660575, 2021). "Subsequently, we investigated MRGBP expression in 39 kinds of cancer cell lines." (PMID 34660575, 2021). "MRGBP expression is frequently amplified in multiple types of cancer." (PMID 33761715, 2021). "Also, we analyzed the relationship between the MRGBP expression and prognostic value in 33 types of cancer using TCGA databases and Kaplan-Meier plotter." (PMID 34660575, 2021). "In addition, the overexpression of MRGBP is involved in the occurrence and development of cancer." (PMID 35924262, 2022). "Furthermore, MRGBP expression in relation to age was observed in certain types of cancers." (PMID 34660575, 2021). "However, it is still unknown the role MRGBP plays in human cancers, which deserves further exploration." (PMID 34660575, 2021). "Therefore, BRD8 may have an important function for cell proliferation as a down-stream target of MRGBP in cancer cells." (PMID 20051959, 2010). "Among them, less MRGBP expression was shown in patients over 65 years of age in ESCA, LIHC, and LUAD, and more expressed in other above cancers." (PMID 34660575, 2021). "Our results showed that MRGBP expression was positively correlated with TMB and MSI in most cancer types." (PMID 34660575, 2021). "We then studied the relationship between the expression of MRGBP and TME in 33 cancers using the ESTIMATE algorithm." (PMID 34660575, 2021). "In summary, increased MRGBP expression correlates with cancer progression, poor survival, and immune infiltration levels in HCC, suggesting that MRGBP may be a novel prognostic biomarker correlated with immune infiltrates." (PMID 33761715, 2021). "We also found a significant negative correlation between MRGBP expression and stromal scores and immune scores in various types of cancer." (PMID 34660575, 2021). "Moreover, MRGBP expression was significantly correlated with poor prognosis, TMB, MSI, and immune cell infiltration in most types of cancer." (PMID 34660575, 2021). "Our observation also showed that knockdown of MRGBP can reduce tumor growth and induced apoptosis in PDAC cells in vitro, which may play an important role in proliferation of cancer cells." (PMID 28969065, 2017). "However, no studies were exploring the role of MRGBP in a variety of cancers." (PMID 34660575, 2021).
tumour (5 papers, 2010 to 2022). "In this study, our data were derived from a combination of public databases and web tools, and R language was used to analyze the association between MRGBP expression and patient prognosis and its potential role in tumor immunity." (PMID 34660575, 2021). "In a multivariate analysis, high MRGBP expression remained independently associated with a poor OS (HR = 1.737 [1.061–2.845]; P = .028), along with the tumor status." (PMID 33761715, 2021). "All this evidence indicated that MRGBP was associated with tumor development as well as patient prognosis." (PMID 34660575, 2021). "MRGBP is involved in a variety of tumor processes, and its expression is significantly increased in a variety of tumors, suggesting that MRGBP may be used as a diagnostic biomarker and therapeutic target for tumors." (PMID 34660575, 2021). "The overexpression of many other amplified genes (e.g., AURKA, HRH3, MIR646, MRGBP, PCK1, PMEPA1, SLCO4A1-AS1, SOX18, TNFRSF6B) is associated with PDAC cell proliferation and tumour growth." (PMID 36289850, 2022). "Meanwhile, MRGBP expression increased in tumour tissues of 43 HNSC samples after reservation paired sample screening (P = 2E − 15)." (PMID 35924262, 2022). "More and more researchers have begun to explore the relationship between MRGBP and tumours in recent years." (PMID 35924262, 2022). "GSEA revealed the abundance of tumour-related pathways, such as cell cycle and DNA replication pathways, in the highly expressed MRGBP phenotype." (PMID 35924262, 2022). "We screened MRGBP binding proteins and MRGBP expression-related genes for a series of pathway enrichment analyses to investigate the molecular mechanisms of MRGBP genes in tumorigenesis and tumor progression." (PMID 34660575, 2021). "The results showed that MRGBP level in tumor tissues was significantly higher than normal tissues in most tumors, which was consistent with previous results." (PMID 34660575, 2021). "The values of MRGBP expression in 50 tumor tissues were remarkably higher than those in 50 paired normal liver tissues in TCGA cohort (P < .001)." (PMID 33761715, 2021). "In conclusion, these results reveal that MRGBP can serve as a potential prognostic biomarker and it plays an important role in tumor immune infiltration in various tumors, especially in LGG and LIHC." (PMID 34660575, 2021). "Next, we analyzed the expression levels of MRGBP in a variety of normal as well as tumor tissues using multiple databases." (PMID 34660575, 2021). "The higher expression of MRGBP correlated significantly with poor tumor status (P = .006), a higher T stage (P < .001), and a higher pathologic stage (P = .003)." (PMID 33761715, 2021). "Using the Wilcoxon signed-rank test, we found that the expression levels of MRGBP in 371 tumor tissues were notably higher than those in 50 normal tissues (P < .001)." (PMID 33761715, 2021). "We combined data from GTEx and TCGA to analyze the differential expression of MRGBP in 27 normal and tumor tissues due to the small number of normal samples in the TCGA database." (PMID 34660575, 2021). "In summary, our results demonstrated high MRGBP expression in a variety of tumors and revealed the correlation between MRGBP expression and tumor progression." (PMID 34660575, 2021). "In this study, we investigated a gene termed as MRGBP (formally C20orf20), because its expression was elevated in 9 out of 11 tumours in our microarray data." (PMID 20051959, 2010).
tumour (continued). "Western blot analysis also showed enhanced MRGBP expression in 10 out of the additional 14 tumours examined." (PMID 20051959, 2010). "They explored the expression profile of MRGBP in 33 tumours." (PMID 35924262, 2022). "MRGBP regulates cell cycle, apoptosis, tumor growth, and invasiveness." (PMID 33761715, 2021). "Furthermore, MRGBP expression in 50 tumor tissues was remarkably higher than that in 50 paired normal liver tissues in TCGA cohort." (PMID 33761715, 2021). "Overall, MRGBP may influence tumor development and ultimately patient prognosis by regulating DNA methyltransferase gene and M6A RNA methylation." (PMID 34660575, 2021). "We next evaluated the differences in MRGBP expression between the tumor and normal tissues." (PMID 34660575, 2021). "When MRGBP is inhibited it induces apoptosis and reduces tumor growth." (PMID 34660575, 2021). "Finally, we performed a series of enrichment analyses by screening out genes closely related to MRGBP expression, and the results showed that MRGBP contributed to tumor development by regulating ganelle fission, nuclear division, mitotic nuclear division, and histone modifications." (PMID 34660575, 2021). "In particular, most of the amplified genes are involved in proliferation and tumour progression in PDAC, such as AURKA, HRH3, MIR646, MRGBP, PCK1, PMEPA1, SLCO4A1-AS1, SOX18, and TNFRSF6B." (PMID 36289850, 2022). "We used Spearman test to analyze the correlation between the expression of MRGBP and immune cell infiltration level, which was quantified using ssGSEA in an HCC tumor microenvironment." (PMID 33761715, 2021).
MRGBP also shares sentences with these, for which no sentence is quoted: cervical cancer (2 papers); adenocarcinoma (1); adrenal cortical carcinoma (1); colorectal adenoma (1); gastrointestinal disease (1); leukemia (1); squamous cell carcinoma (1); type 1 diabetes mellitus (1); urothelial bladder carcinoma (1).